CENPU (centromere protein U)
Description:
Component of the CENPA-NAC (nucleosome-associated) complex, a complex that plays a central role in assembly of kinetochore proteins, mitotic progression and chromosome segregation. The CENPA-NAC complex recruits the CENPA-CAD (nucleosome distal) complex and may be involved in incorporation of newly synthesized CENPA into centromeres. Plays an important role in the correct PLK1 localization to the mitotic kinetochores. A scaffold protein responsible for the initial recruitment and maintenance of the kinetochore PLK1 population until its degradation. Involved in transcriptional repression.
Synonyms: CENP-U; CENP-50; KLIP1; MLF1IP; PBIP1; CENP50; CENPU50
Tractability: PROTAC: UniProt records ubiquitination sites on it; ubiquitination databases record sites on it.
Gene: Protein-coding gene on chromosome 4 (184,694,085 to 184,734,130, reverse strand). Ensembl gene ENSG00000151725.
Subcellular location: Cytoplasm; Nucleus; Chromosome, centromere, kinetochore
Subcellular location (Human Protein Atlas): Centriolar satellite; Nucleoplasm
Pathways (Reactome):
Cell Cycle: Amplification of signal from unattached kinetochores via a MAD2 inhibitory signal; Deposition of new CENPA-containing nucleosomes at the centromere; EML4 and NUDC in mitotic spindle formation; Mitotic Prometaphase; Resolution of Sister Chromatid Cohesion; Separation of Sister Chromatids
Signal Transduction: RHO GTPases Activate Formins
Gene Ontology:
Molecular function: protein binding
Biological process: chromosome segregation
Cellular component: centriolar satellite; inner kinetochore; nucleoplasm; cytosol; nucleus; cytoplasm
Genetic constraint (gnomAD): Loss-of-function variants: 20 observed, 24.08 expected, observed/expected ratio (o/e) 0.83, 90% interval 0.58 to 1.21. The upper end of that interval is the gene's LOEUF score, 1.21, which puts it in group 5 of 6, group 1 being the genes least tolerant of losing a copy. Missense variants: 289 observed, 284.65 expected, observed/expected ratio (o/e) 1.02, 90% interval 0.92 to 1.12. Synonymous variants: 94 observed, 99.83 expected, observed/expected ratio (o/e) 0.94, 90% interval 0.8 to 1.12.
Homologues: Orthologues: chimpanzee CENPU (98% identical), macaque CENPU (90% identical), pig CENPU (71% identical), guinea pig CENPU (66% identical), dog CENPU (63% identical), rabbit CENPU (62% identical), mouse Cenpu (56% identical), rat Cenpu (50% identical), tropical clawed frog cenpu (33% identical), zebrafish cenpu (20% identical).
Diseases named in the same sentence as CENPU in open-access papers:
CENPU is named in the same sentence as 31 diseases in open-access papers, as found by Europe PMC text mining. Sharing a sentence is not in itself a finding about the gene and the disease. The quoted sentences say what the papers report.
breast carcinoma (9 papers, 2020 to 2023). "Accordingly, DBH-AS1 has been linked to viral-mediated hepatocellular carcinoma, while GATA3-AS1 is associated with poor prognosis in breast cancer via the GATA3-AS1/miR-495-3p/CENPU axis." (PMID 35201514, 2021). "Next, we explored the mechanism underlying CENPU’s prognostic value in breast cancer." (PMID 33902008, 2021). "Also, CENPU expression significantly correlated with clinical and pathological features of breast carcinoma patients, especially patients with TNBC, implying that the expression of CENPU was closely linked to progression of breast carcinoma." (PMID 33902008, 2021). "We first analyzed CENPU gene mutations in breast carcinoma patients and found a relatively low incidence of CENPU gene mutation, implying that CENPU gene mutation might not be the key reason for the differences in its mRNA level." (PMID 33902008, 2021). "It is worth mentioning that the four verified lncRNAs as a miRNA sponge are widely reported in cancers, such as the GATA3-AS1/miR-495-3p/CENPU axis in breast cancer, and the PWRN1/miR-214-5p axis in osteosarcoma." (PMID 36874970, 2023). "Downregulation of CENPU can suppress the proliferation of breast cancer cells and cycle progression and further increase apoptosis." (PMID 35028418, 2022). "It has been shown that Centromere Protein U (CENPU) reduces ubiquitination as well as degradation of COX-2 in breast cancer." (PMID 35055142, 2022). "Subsequently, differences in CENPU expression in breast carcinoma patients with different clinical and pathological parameters were determined based on bc-GenExMiner." (PMID 33902008, 2021). "Then we used the PrognoScan database to assess the correlation between CENPU expression and prognosis of breast carcinoma patients." (PMID 33902008, 2021). "Combination of the results from expression, survival, correlation analysis and functional experiments analysis demonstrated the link between lncRNA GATA3-AS1/miR-495-3p/CENPU axis and prognosis of breast cancer." (PMID 33902008, 2021). "Taken together, these data imply that CENPU is a molecular indicator for breast carcinoma, especially for TNBC." (PMID 33902008, 2021). "Relationship between CENPU expression and prognosis in breast cancer patients from PrognoScan database." (PMID 33902008, 2021). "We found significant correlation between CENPU expression and the age of breast cancer patients, with higher CENPU expression levels being observed in patients aged ≤51 years than in patients aged >51 years." (PMID 33902008, 2021). "CENPU is reported to be abnormally high expressed in various human tumor tissues and is involved in tumor progression, such as prostate cancer, breast cancer, bladder cancer, and ovarian cancer, and its overexpression has been shown to predict poor prognosis." (PMID 34712733, 2021). "Next, based on the PrognoScan database, we explored the prognostic significance of CENPU expression in breast carcinoma and found that higher CENPU expression levels were predictive of a poorer prognosis." (PMID 33902008, 2021). "All these data suggest that CENPU is not only an indicator of breast cancer, but also a molecular indicator of triple-negative breast carcinoma." (PMID 33902008, 2021). "All these data suggest that CENPU expression is also an indicator of prognosis of breast carcinoma patients." (PMID 33902008, 2021). "Combined with the results obtained from the expression analysis, survival analysis, and correlation analyses, these functional experiments demonstrate a link between the lncRNA GATA3-AS1/miR-495-3p/CENPU axis and the prognosis of breast cancer patients." (PMID 33902008, 2021). "In our current study, we also tried to identify miRNAs and lncRNAs that can regulate CENPU expression in breast cancer." (PMID 33902008, 2021). "Overexpression of CENPU is related to breast cancer, lung cancer, ovarian cancer and prostate cancer." (PMID 32266115, 2020).
breast carcinoma (continued). "In addition, we discovered that high levels of CENPU expression predicted poor prognosis in patients with breast cancer." (PMID 33902008, 2021). "We next explored the prognostic significance of CENPU expression in breast cancer." (PMID 33902008, 2021). "Similarly, high CENPU expression was correlated with higher hazard ratios in breast carcinoma patients." (PMID 33902008, 2021). "Our previous study demonstrated that CENPU downregulation might inhibit the proliferation of human breast cancer cells." (PMID 33902008, 2021). "Subsequently, we aimed to explore how CENPU was regulated in breast cancer." (PMID 33902008, 2021). "Furthermore, CENPU expression correlated significantly with many clinicopathological characteristics of breast cancer." (PMID 33902008, 2021). "Therefore, we explored the expression profiles of CENPU gene in breast carcinoma to better understand the functions of this gene, as well as the relationship between CENPU expression and the prognosis of breast carcinoma patients." (PMID 33902008, 2021). "Therefore, it is important to explore the functions of CENPU and its relationship with survival outcomes and pathohistological characteristics in breast carcinoma patients." (PMID 33902008, 2021). "The function of centromere protein U (CENPU) gene in breast cancer has not been well understood." (PMID 33902008, 2021). "Taken together, these data indicate a low incidence of CENPU gene mutation in breast carcinoma patients, implying that CENPU gene mutation might not be the reason for the differences in gene expression." (PMID 33902008, 2021). "Taken together, these findings imply that CENPU may be a potential biomarker for breast carcinoma." (PMID 33902008, 2021). "Recently, multiple studies have suggested the aberrant expression of CENPU in various human solid tumors, such as non-small-cell lung cancer (NSCLC), bladder cancer, ovarian cancer, and breast cancer, which highlights the crucial role of CENPU in these tumors." (PMID 34957303, 2021). "We found that CENPU expression significantly correlated with overall survival (OS), distant metastasis-free survival (DMFS), and relapse-free survival (RFS) in breast carcinoma patients." (PMID 33902008, 2021). "Furthermore, CENPU was markedly upregulated in patients with lymph node metastasis, as well as in estrogen receptor (ER)-negative, progesterone receptor (PR)-negative, and human epidermal growth factor receptor 2 (HER2)-positive breast carcinoma patients." (PMID 33902008, 2021).
hepatocellular carcinoma (6 papers, 2019 to 2023). A malignant tumor that arises from hepatocytes. "Centromere protein U (CENPU) has been shown to accelerate the G1/S transition of hepatocellular carcinoma cell proliferation by interacting with E2F6 and affecting transcription of E2F1." (PMID 37292517, 2023). "Based on these findings, we propose that E2F6 is required for CENPU-mediated proliferation, migration, and cell cycle progression of hepatoma cells." (PMID 35844791, 2022). "Cellular phenotypic experiments indicated that CENPU promoted the proliferation, metastasis, and cell cycle progression of hepatoma cells in vivo and in vitro." (PMID 35844791, 2022). "Taken together, these findings indicated that suppression of CENPU blocked the transition from G1 to S phase in hepatoma cells." (PMID 35844791, 2022). "In this research, we identified for the first time that CENPU is an oncogene that promotes hepatoma cell proliferation, migration, and G1/S transition in vitro and in vivo." (PMID 35844791, 2022). "Centromere protein U (CENPU), a centromere-binding protein required for cellular mitosis, has been reported to be closely associated with carcinogenesis in multiple malignancies; however, the role of CENPU in hepatocellular carcinoma (HCC) is still unclear." (PMID 35844791, 2022). "Additionally, CENPU promoted hepatoma cell proliferation, invasion, migration, and cell cycle progression." (PMID 35844791, 2022). "Likewise, hepatoma cell lines had higher CENPU expression than the normal hepatocyte line L02 at both the protein and mRNA levels." (PMID 35844791, 2022).
gastric cancer (5 papers, 2019 to 2025). A primary or metastatic malignant neoplasm involving the stomach. "This study demonstrated that downregulation of CENPU inhibited cell proliferation and glycolysis of gastric cancer by regulating HMGB2." (PMID 34872447, 2021). "To investigate the regulatory role of CENPU in proliferation of gastric cancer cells, we used siRNA gene silencing and detected cell proliferation in AGS cell line." (PMID 34872447, 2021). "GEPIA (Gene Expression Profiling Interactive Analysis) revealed that CENPU was upregulated in gastric cancer cells." (PMID 34872447, 2021). "In this work, we aimed to investigate the regulatory role of CENPU in gastric cancer and its correlation with HMGB2, and their effects on glycolytic metabolism." (PMID 34872447, 2021). "The results showed that CENPU expression was upregulated in esophageal cancer, stomach cancer, pancreatic cancer, HCC, colon cancer, and rectal cancer tissues compared with normal tissues." (PMID 34957303, 2021). "In the present study, we demonstrated that CENPU promoted proliferation and glycolysis of gastric cancer cells via HMGB2." (PMID 34872447, 2021). "CENPU was an upstream protein of HMGB2, and CENPU enhances the expression level of HMGB2 in gastric cancer cells." (PMID 34872447, 2021). "CENPU (Centromere Protein U) is pivotal for gastric cancer development." (PMID 41220952, 2025). "Inhibition of CENPU expression suppressed proliferation and glycolysis of gastric cancer cells." (PMID 34872447, 2021). "In this work, we identified that CENPU was upregulated in gastric cancer." (PMID 34872447, 2021). "CENPU may act as a biomarker for the diagnosis and therapeutic target for the treatment of gastric cancer." (PMID 34872447, 2021). "First, we checked the expression level of CENPU in gastric cancer." (PMID 34872447, 2021). "Knockdown of CENPU was able to suppress the proliferation and glycolysis of gastric cancer cells." (PMID 34872447, 2021). "We showed that CENPU was upregulated in gastric cancer cell lines." (PMID 34872447, 2021). "Additionally, CENPU facilitates energy provision during cell division by closely coordinating with the cell cycle, enabling tumor cells to acquire more metabolic intermediates during proliferation, thus advancing gastric cancer development." (PMID 41220952, 2025). "Thus, targeting CENPU is a promising therapeutic strategy for treatment of gastric cancer." (PMID 34872447, 2021). "In this work, we identified that CENPU is upstream of HMGB2, which regulated proliferation and glycolysis of gastric cancer." (PMID 34872447, 2021). "Taken together, CENPU is an upstream factor of HMGB2, which regulates proliferation and glycolysis of gastric cancer." (PMID 34872447, 2021). "In summary, CENPU was an upstream protein of HMGB2, which regulated proliferation and glycolysis of gastric cancer." (PMID 34872447, 2021). "Next the effect of CENPU on the expression level of HMGB2 and their roles in proliferation and glycolysis in gastric cancer cells were investigated." (PMID 34872447, 2021). "Knockdown of CENPU by siRNA gene silencing suppressed the proliferation and glycolysis activity of AGS gastric cancer cells." (PMID 34872447, 2021). "qPCR and Western blotting analysis showed that in gastric cancer cell lines AGS, MKN45 and HGC-27, the mRNA level and the relative protein expression level of CENPU were significantly increased, compared with human gastric epithelial cell line GES-1." (PMID 34872447, 2021). "TCGA shows that CENPU is upregulated in gastric cancer, but its biological function and mechanism are still not clear." (PMID 34872447, 2021).
lung carcinoma (5 papers, 2019 to 2023). "CENPF (Centromere protein F) is a gene related to chromosome segregation during mitosis that reduces overall survival in lung cancer and is a hub gene (AURKB, BUB1B, KIF2C, HMMR, CENPF, and CENPU) overexpressed in cancer patients." (PMID 36661515, 2023).
ovarian carcinoma (5 papers, 2018 to 2021). A malignant neoplasm originating from the surface ovarian epithelium. "HMGB2 is found to be downstream of CENPU, and CENPU promoted malignancy and development of ovarian cancer via HMGB2." (PMID 34872447, 2021). "Recent researchers revealed that CENPU highly expressed in ovarian cancer samples and that overexpression of CENPU augments ovarian cancer aggressiveness by regulating high-mobility group box 2 (HMGB2)." (PMID 34957303, 2021). "HMGB2 is identified as a downstream factor of CENPU, and CENPU enhances the expression level of HMGB2 in ovarian cancer cells." (PMID 34872447, 2021). "CENPU facilitates aggressiveness ability and progression of ovarian cancer via HMGB2." (PMID 34872447, 2021).
bladder cancer (4 papers, 2018 to 2021). "CENPU is elevated in human bladder cancer tissues compared with surrounding tissues, and high CENPU expression is obviously associated with tumor size, TNM stage, and poor prognosis." (PMID 34957303, 2021).
prostate carcinoma (4 papers, 2018 to 2021). A carcinoma that arises from epithelial cells of the prostate gland. "CDC25C, CDCA5, TOP2A, and CENPU, genes whose expression levels were strongly correlated to CENPA expression in prostate cancer tissue, were all notably down-regulated with CENPA depletion, as well as bound by CENPA." (PMID 32371391, 2020).
triple-negative breast carcinoma (4 papers, 2021). An invasive breast carcinoma which is negative for expression of estrogen receptor (ER), progesterone receptor (PR), and human epidermal growth factor receptor 2 (HER2). "Another study on triple-negative breast cancer showed that COX-2 protein was upregulated because the ubiquitination and proteasomal degradation were inhibited by centromere protein U (CENPU; a centromere component essential for mitosis)." (PMID 34316376, 2021).
non-small cell lung carcinoma (2 papers, 2021 to 2022). A group of at least three distinct histological types of lung cancer, including non-small cell squamous cell carcinoma, adenocarcinoma, and large cell carcinoma. "For instance, in non-small-cell lung cancer, CENPU expression promotes cancer cell proliferation and forecasts poor survival." (PMID 35496042, 2022).
liver cancer (1 paper, 2022). An epithelial or non-epithelial malignant neoplasm that arises from the liver. "Moreover, clinical data analysis showed that a high level of CENPU expression was linked to tumour grade, stage, portal vein tumour thrombus (PVTT), and Barcelona Clinic Liver Cancer (BCLC) stage." (PMID 35844791, 2022).
lung adenocarcinoma (1 paper, 2021). A carcinoma that arises from the lung and is characterized by the presence of malignant glandular epithelial cells. "A study has demonstrated that CENPU regulated the proliferation and migration of lung adenocarcinoma cells through the PI3K/AKT pathway; however, there are no data on the carcinogenic effect and clinical significance of CENPU in SCLC." (PMID 34712733, 2021).
periodontitis (1 paper, 2024). An acute or chronic inflammatory process that affects the tissues that surround and support the teeth. "Additionally, C1QA exhibited a correlation with inflammation in geneCards, which implied that CENPK, CENPU and BST2 could feasibly manifest as factors linked to periodontitis." (PMID 38919957, 2024). "BST2, CENPU and CENPK are the potential undiscovered genes that are related to the regulation of periodontitis." (PMID 38919957, 2024). "The identified biomarkers C1QA, CENPK, CENPU, BST2 and LINC01133 provided valuable insight into periodontitis pathology." (PMID 38919957, 2024).
pulmonary disorder (1 paper, 2022). "Based on pathway enrichment analysis, genes altered in BPD blood cells were mainly enriched in cell cycle regulation and arrest (e.g., PPP2CA, RBL2, CENPU, CCNY, CDK6) and pulmonary disorder and developmental disorders (e.g., AGER, ITGA6, CA4, BACH2, IGFBP2, BMPR2, SKI, DAB2)." (PMID 35484630, 2022).